TNF (tumor necrosis factor)
Diseases named in the same sentence as TNF in open-access papers (continued):
Sharing a sentence is not in itself a finding about the gene and the disease.
Arterial thrombosis (5 papers, 2013 to 2025). The formation of a blood clot inside an artery. "In this study we investigated the influence of SHP-1 on platelet-endothelium interaction and arterial thrombosis in TNFα-induced endothelial inflammation in vivo." (PMID 23766558, 2013). "Mounting evidence suggests that cytokines like tumor necrosis factor-α (TNF-α) and angiotensin-II (Ang II) are increased in human arterial thrombosis." (PMID 32337281, 2020).
asthenozoospermia (5 papers, 2017 to 2025). "In CTX induced asthenospermia mouse model, the levels of TNF-α and IL-6 in serum were higher than those in the control group (p < 0.01)." (PMID 36142279, 2022). "Notably, inflammation seems to play an important role in the etiology of asthenozoospermia, and TNF-a as a central regulator of inflammation had been reported significantly higher in asthenozoospermia patients compared with health controls." (PMID 36337657, 2022). "The asthenospermia mouse model showed high activity of MDA and proinflammatory factors (TNF-α, IL-6), as well as low expression of antioxidants (SOD, GSH-Px, CAT) in the testis and epididymis, but this situation could be significantly ameliorated after being treated with CNP." (PMID 36142279, 2022).
Ataxia (5 papers, 2017 to 2025). Ataxia refers to impaired coordination of voluntary muscle movement. "The sphingolipid signaling pathway belongs in the same cluster with MAPK signaling and TNF-signaling pathways in neuronal “ataxia” datasets, while the sphingolipid metabolism is found in the same cluster with autophagy and Rap1 signaling pathway." (PMID 32937819, 2020). "Mice expressing IL-6 and TNF-a in astrocytes suffer ataxia, inflammation and neurodegeneration after MV infection." (PMID 29312244, 2017).
Atherosclerotic lesion (5 papers, 2018 to 2024). A lesion associated with atherosclerosis, a multifactorial and multipart progressive disease manifested by the focal development within the arterial wall of lesions, that ranges from the development of a fatty streak, plaque progression, and plaque disruption. "Our study aimed to assess the influence of tumor necrosis factor-alpha (TNF), a proinflammatory cytokine abundantly found in atherosclerotic lesions, on endothelial laminin gene expression and the effects of laminin-332 (LN332) on endothelial cells’ behavior." (PMID 39201392, 2024). "Results showed that LECT2 reduced total cholesterol and low-density lipoprotein concentrations in serum and inhibited the development of atherosclerotic lesions, accompanied by reductions in inflammatory cytokines and lower MCP-1, MMP-1, TNF-α, IL-8, and IL-1β mRNA abundance." (PMID 31310065, 2019).
B cell deficiency (5 papers, 2016 to 2025). A broad classification of disorders where circulating numbers of B lymphocytes are decreased or ineffective. "We found decreased expression of RANTES, MCP-5, IP-10, CXCL11, and TNF following B cell deficiency or depletion in MRL/lpr mice." (PMID 27055816, 2016). "B-cell deficiency did not affect expression of IL1β nor other DAM genes, such as TNFα, Igf1, and Lilrb4." (PMID 33846335, 2021).
behavioral disorders (5 papers, 2018 to 2025). "Findings showed that the number of tonic-clonic seizures, atrophy, and cell death in the hippocampus and cerebellum, the gene expression of TNF-α and IL-1β in the hippocampus, and behavioral disorders were significantly increased in the hypoxia rats compared to the sham group." (PMID 39483191, 2024).
Burkitt lymphoma (5 papers, 2013 to 2022). A rare form of malignant mature B-cell non-Hodgkin lymphoma. "BAX/BAK complex was already reported in other apoptotic responses, as in HeLa cells treated with TNF-α and in Burkitt’s lymphoma cells upon verotoxin-1 treatment." (PMID 32371863, 2020). "The B-lymphocytic Raji cell lines, derived from Burkitt’s lymphoma, that did not possess a membrane bound TNFα receptor, were unaffected by TNFα treatment." (PMID 34069352, 2021).
calcification (5 papers, 2015 to 2021). Process by which organic tissue becomes hardened by the physiologic deposit of calcium salts. "The production of TNFα in microglia could be affected by miR32-5p targeting PIKfyve, and these results will be beneficial to reveal the mechanism of brain arterial calcification." (PMID 31952480, 2020). "We used HASMC to investigate the role of TNF-α, oxidative stress and TNFR1 in inducing aortic calcification and to elucidate the mechanism contributes the protective effect of SIM against aortic calcification." (PMID 26625143, 2015). "Therefore, vascular calcifications do not seem to depend on the values of the calcium/phosphataemia, but are influenced by the Receptor activator of nuclear factor-kappa-Β ligand (RANKL) activation pathway belonging to the tumor necrosis factor (TNF) super-family." (PMID 34070202, 2021).
capillary leak syndrome (5 papers, 2015 to 2025). A syndrome characterized by leakage of intravascular fluids into the extravascular space. "While TNFα is an important cytokine in immunotherapy, high levels of TNFα can result in capillary leak syndrome, which, if unchecked, can lead to hypovolemic shock." (PMID 25592450, 2015). "Although CD123 expression on endothelial cells is very low, high levels of interferon-γ and tumor necrosis factor-α induced by cytokine release syndrome may facilitate CD123 expression and trigger capillary leak syndrome (CLS)." (PMID 33525388, 2021).
cardiac sarcoidosis (5 papers, 2020 to 2025). Sarcoidosis affecting the tissues of the heart. "Certain international consensus guidelines recommend the use of methotrexate and tumor necrosis factor-alpha inhibitors like infliximab or adalimumab in severe or refractory cases of cardiac sarcoidosis, especially as second- and third-line agents, which also aim to minimize steroid exposure." (PMID 39118165, 2024). "In cases of cardiac sarcoidosis, anti-TNF therapies may offer therapeutic advantages." (PMID 39867510, 2025).
cardioembolic stroke (5 papers, 2020 to 2025). "Several studies reported that elevated levels of the inflammatory biomarkers, c-reactive protein (CRP), tumor necrosis factor-α (TNF-α), interleukin-6 (IL-6), interleukin-1β (IL-1β), are associated with cardioembolic stroke." (PMID 33050269, 2020). "For example, evidence suggests that inflammatory biomarkers like C-reactive protein (CRP), IL (interleukin)-6, IL-1b, TNF-a and D-dimer alongside cardiac biomarkers such as B-type natriuretic peptide (BNP) or its N-terminal fragment, NT-pro-BNP are all associated with cardioembolic stroke." (PMID 40117100, 2025).
Castleman disease (5 papers, 2014 to 2024). Castleman disease (CD) is a benign lymphoproliferative disorder that may present as a localized or multicentric form. "Certain cytokines have been reported in cases of Castleman disease, including IL-6, VEGF, tumor necrosis factor-α(TNF-α), IL-1, and IL-8." (PMID 34208103, 2021).
cervical intraepithelial neoplasia (5 papers, 2014 to 2025). "Cytokines, such as TNF-α and MIP-1β, are associated with the progression of BV to cervical intraepithelial neoplasia (CIN)." (PMID 36552306, 2022). "This study therefore estimated and compared the levels of circulatory IL-4, IL-6, IL-10, TNF-α, and IFN-γ cytokines among adult women identified to have different grades of cervical intraepithelial neoplasia (CIN) and with cervicovaginal infection." (PMID 37635942, 2023). "We have previously shown that the HPV induced cervical dysplasia in patients with decreased serum levels of IFN-γ and IFN-α while increasing the levels of pro-inflammatory cytokines, TNF-α and IL-1β, and cytokine Th-2 type, IL-4." (PMID 24386936, 2014).
corneal infection (5 papers, 2017 to 2025). A viral or bacterial infectious process affecting the cornea. "Pro-inflammatory cytokines like IL-1, IL-6 and TNF-α produces by keratocytes is also an important factor causing corneal ulcer." (PMID 28448563, 2017). "Specifically, glutamine treatment effectively attenuates endotoxin-induced canine corneal ulceration by suppressing the NF-κB pathway, alongside its downstream TNF-α and IL-6 signaling." (PMID 39837870, 2025). "During corneal infections, pro-inflammatory cytokines like IL-1β, IL-6, and tumor necrosis factor (TNF)-α are released that triggers different signaling pathways leading to collagen degradation in the stroma as well as necrotic death of keratocytes." (PMID 34458234, 2021). "It is possible that one of important mechanisms of corneal ulcer reduction might be related to downregulation of inflammatory cytokines, especially TNFα and NF-ḳB, and the increased expression of FOXO3 induced by SAHA application." (PMID 31285488, 2019).
coronary artery calcification (5 papers, 2014 to 2025). Calcification of the coronary artery, used as a measure of coronary atherosclerosis, a risk factor for myocardial infarction. "The upregulation of IL-10 expression and concomitant reduction in TNF and IL-18 production were identified as direct immunoregulatory mechanisms through which IL-37 ameliorated atherosclerosis and coronary artery calcification." (PMID 39337246, 2024). "Additionally, patients with coronary artery calcification showed significantly increased plasma IL-37 concentrations, with correlation analysis revealing positive associations between IL-37 levels and age, fasting glucose, alkaline phosphatase, IL-6, TNF, and C-reactive protein." (PMID 39337246, 2024). "Furthermore, considering higher miR32 levels in plasma of patients with coronary artery calcification, the influence of miR32-5p for microglia producing TNFα was analysed." (PMID 31952480, 2020).
deafness (5 papers, 2020 to 2026). An inherited or acquired condition characterized by the complete loss of the ability to hear from one or both ears. "Beyond mouse experiments, TNF-α and IL-6 levels were significantly higher in the perilymph fluid of humans with deafness." (PMID 35010640, 2021). "In noise-induced deafness, proinflammatory cytokines or chemokines, including TNF-α, IL-1β, IL-6, Icam-1, and Ccl2, were increased in cells of the stria vascularis or lateral wall." (PMID 33505961, 2020).
diffuse cutaneous Leishmaniasis (5 papers, 2016 to 2025). A form of LEISHMANIASIS, CUTANEOUS caused by Leishmania aethiopica in Ethiopia and Kenya, L. pifanoi in Venezuela, L. braziliensis in South America, and L. mexicana in Central America. "An important NK-cell inhibition with reduced TNF-α, IFN-γ and TLR2 expression had previously been identified in patients with diffuse cutaneous leishmaniasis (DCL) infected with Leishmania mexicana." (PMID 27031998, 2016). "Patients with localized cutaneous lesion (LCL) exhibit predominant expression of iNOS, IL-1β, IL-6, MCP-1, TNF-α, and IFN-γ, while anergic diffuse cutaneous leishmaniasis (ADCL) lesions are characterized by the presence of IL-4, IL-5, IL-10, and MIP-1α and the low expression of iNOS." (PMID 28959260, 2017).
DRESS syndrome (5 papers, 2017 to 2024). "Activated T lymphocytes produced large amounts of tumor necrosis factor-α, interleukin-2, and interferon-γ and considered key mediators of the cytokine release that induces the symptoms found in DRESS syndrome patients." (PMID 39280124, 2024). "As elevated levels of TNF‐alpha, chemokines and cytokines have been detected at the onset of DRESS Syndrome as well as in TEN‐patients treatment with a TNF‐alpha antibody seems plausible for both." (PMID 36751314, 2023). "Expanded CD8+ T cells from patients with DRESS syndrome could recognize one of several EBV epitopes and are capable of the production of large amounts of tumor necrosis factor (TNF)-α and IFN-γ." (PMID 28598363, 2017).
eating disorder (5 papers, 2020 to 2024). A broad group of psychological disorders with abnormal eating behaviors leading to physiological effects from overeating or insufficient food intake. "In another young transdiagnostic sample including male and female patients with AN and other eating disorders (mean age 17.7 years for female participants), patients showed normal serum TNF-α levels and lower concentrations of IL-6 and the pro-inflammatory cytokine IL-1 beta." (PMID 38461330, 2024). "One hypothesis posits that elevated levels of pro-inflammatory cytokines (IL-6 and TNF-α) in patients with IBD may contribute to the perpetuation of eating disorder symptoms." (PMID 39050133, 2024). "The eating disorder is predicted to increase with six DRGs, which are LEP, IL6, GCG, SERPINE1, TNF, and INS." (PMID 32753925, 2020).
End Stage Liver Disease (5 papers, 2010 to 2025). Final stage of a liver disease when the liver failure is irreversible and LIVER TRANSPLANTATION is needed. "It was reported that in patients with end-stage liver disease, the body’s immune system and inflammatory response were over-activated with a large number of inflammatory factors being released into the bloodstream (e.g., IL-6, IL-8, TNF-α, etc.), which caused damage to hepatocytes." (PMID 32938405, 2020). "A key circulating proinflammatory cytokine in end-stage liver disease is TNF, which contributes to endothelial damage and promotes vascular permeability and vasodilation via a nitric oxide–mediated pathway." (PMID 41020850, 2025). "The rate of progression to end-stage liver disease might be related to an up-regulation of the TNF-α/Fas pathways and an age-dependent host response." (PMID 20051112, 2010). "Increased baseline model for end-stage liver disease score, white cell count, calprotectin, CD163, tumor necrosis factor, renin, atrial natriuretic peptide, and syndecan-1 were associated with 3-month mortality." (PMID 35333783, 2022). "Patients who died within 3 months of trial entry had significantly higher model for end-stage liver disease (MELD) score, serum white cell count, CD163, and TNFα at baseline compared with those who survived." (PMID 35333783, 2022).
eosinophilic esophagitis (5 papers, 2019 to 2024). Eosinophilic esophagitis (EoE) is a chronic, allergic disease of the esophagus characterized clinically by symptoms of esophageal dysfunction (including vomiting, dysphagia, feeding disorders, food impaction and abdominal pain) which persist after treatment with proton pump inhibitors (PPIs). "The tumor necrosis factor (TNF)/NF-κB pathway has been reported to mediate the activation of esophageal eosinophils in eosinophilic esophagitis." (PMID 38493955, 2024). "However, the key targets obtained using this approach are not primary drivers of eosinophilic esophagitis but based on the evidence on the literature the role of TNF in EoE has been actively investigated." (PMID 36591238, 2022). "Finally, as there are similarities in the pathogenesis of EC with eosinophilic esophagitis (EoE), biologic medications undergoing clinical trials for the treatment of EoE are potential therapeutic agents for EC (Anti-IL5, anti-IgE monoclonal antibodies, anti-tumor necrosis factor (TNF-α)." (PMID 38238810, 2024).
folliculitis (5 papers, 2022 to 2026). Inflammation of the hair follicles. "Concerning previous treatment strategy challenges, immunomodulators are novel treatment agents acting by downregulating the immune system and decreasing inflammatory mediators such as TNF-α, IL-17, and IL-23, which are crucial factors for developing follicular disorders like DCS." (PMID 40383754, 2025).
gram-positive bacterial infections (5 papers, 2013 to 2023). Infections caused by bacteria that retain the crystal violet stain (positive) when treated by the gram-staining method. "A notable problem with implementation of TNF-α as a routine diagnostic biomarker is its undetectable serum level in a significant percentage of patients with a proven Gram-positive bacterial infection of moderate disease severity." (PMID 23690657, 2013). "Upon stimulation by proinflammatory cytokines such as IL-1β and TNF-α, as an important lipit mediator, PGE2 synthesis is upregulated following Gram-negative and Gram-positive bacterial infection." (PMID 29874233, 2018).
hemophilia (5 papers, 2019 to 2026). Hemophilia is a genetic disorder characterized by spontaneous hemorrhage or prolonged bleeding due to factor VIII or IX deficiency. "Eligible studies evaluated TNF-α polymorphisms in patients with hemophilia and reported data on inhibitor status." (PMID 41653417, 2026). "In a non-hemophilia setting, TNF-α and VEGF-A have been reported to be associated with pathological angiogenesis, with disrupted vascular integrity, vascular leakage, and infiltration of inflammatory cells." (PMID 31892201, 2019). "In summary, the results obtained from the hemophilia mouse model and patients with hemophilic arthropathy show that TNFα is associated with the pathogenicity of hemophilic arthropathy." (PMID 31892201, 2019). "In HA patients, elevated TNF-α levels were significantly associated with the number of hemarthroses, the grade of synovial hypertrophy, and both the clinical World Federation of Hemophilia score and ultrasound score." (PMID 31261789, 2019). "There is only limited clinical data to support the administration of anti-TNFα for hemophilia management." (PMID 31892201, 2019). "In the present study, elevated TNFα in the synovial lavage was identified in a hemophilia mouse model and patients with hemophilic arthropathy." (PMID 31892201, 2019). "Elevated TNFα in synovial lavage was found in the hemophilia mice and patients with hemophilic arthropathy." (PMID 31892201, 2019). "As far as human HA is concerned, to our knowledge, the TNF-α/TNF receptor (TNF-R) system has not been specifically investigated apart from two former studies reporting increased levels of TNF-α in supernatants of cultured hemosiderotic synovial tissue from hemophilia patients." (PMID 31261789, 2019).
hippocampal atrophy (5 papers, 2024 to 2026). "Our results show a significant correlation between increased CSF TNF-α levels and hippocampal atrophy." (PMID 41960503, 2026). "TNFα and IL-1β signaling may represent a more chronic component of stress that contributes to hippocampal atrophy." (PMID 39595087, 2024).
hypophosphatemia (5 papers, 2007 to 2024). Lower than normal levels of phosphates in the circulating blood. "Similarly, severe hypophosphatemia was induced by infusion of recombinant TNF in 22 patients with liver metastases." (PMID 18159256, 2007).
imbalance (5 papers, 2017 to 2025). "Among the PwP, changes in plasma EV-derived IL-1β, TNF-α and IL-6 levels were significantly associated with changes in the severity of postural instability and gait disturbance (PIGD) and cognition." (PMID 36897204, 2023). "This immune imbalance is similarly implicated in the development of DeP, where chronic inflammation and excessive inflammatory responses release pro-inflammatory cytokines (e.g., IL-6, TNF-α) that affect the central nervous system." (PMID 41212883, 2025). "Of the non-motor symptoms, postural instability showed a significant association with serum TNFα levels while postural dizziness showed a significant association with serum NOx levels." (PMID 30954070, 2019). "APS can efficiently inhibit Cd-induced immune imbalance in chicken PBLs through the regulation of MDA5/NF-κB signaling, and it can decrease Cd-induced expression of cytokines (IL-1β, IL-6, and TNF-α)." (PMID 28946702, 2017).